IL17A (interleukin 17A)
Diseases named in the same sentence as IL17A in open-access papers (continued):
Sharing a sentence is not in itself a finding about the gene and the disease.
psoriasis (continued). "Different IL-17 proteins are linked to distinct biological activities i.e. IL-17A is associated with chronic obstructive pulmonary disease (COPD), while IL-17F in psoriasis and rheumatoid arthritis." (PMID 38983855, 2024). "Specifically, Ligilactobacillus and Anaeroplasma are positively correlated with various psoriasis-related factors such as IL-6, IL-17A, IL-22, and IL-23, while Rikenella, Alistipes, and Mucispirillum are negatively correlated with them." (PMID 39170985, 2024). "While Th17 differentiation is induced by IL-6 and TGF-β, IL-23 is essential for Th17-cell function and production of key cytokines in psoriasis, such as IL-17A, IL-17F, IL-22, and TNF- α." (PMID 38731900, 2024). "As a PhD candidate, she concentrated on the role of the cytokines IL-6 and IL-17A in vascular dysfunction development and on the cardiovascular comorbidity in the IL-17A-driven autoimmune skin disease psoriasis." (PMID 39015379, 2024). "The results showed a similar trend in the changes in LCFAs in IMQ-treated WT and Tcrd−/− mice compared to the metabolic changes in LCFAs in psoriasis patients receiving pretherapy and posttreatment with anti-IL-17A mAb." (PMID 38185620, 2024). "The monoclonal antibody secukinumab is specifically designed to selectively target and suppress the pro-inflammatory cytokine IL-17A, which play a pivotal role in autoimmune diseases, such as psoriasis, ankylosing spondylitis, and psoriatic arthritis." (PMID 38605952, 2024). "For the treatment of psoriasis, antibodies against IL‐17A or IL‐17 receptor are approved and are being evaluated for treatment of inflammatory diseases and cancers." (PMID 37899663, 2024). "Therapeutic targeting of IL-17A has shown substantial promise as treatment of psoriasis, PsA, and AS, which has revolutionized the management of these inflammatory diseases, leading to improved clinical outcomes for the patients." (PMID 38292069, 2024). "SFAs, such as palmitic acid (5787.41 ± 718.52 μM) and stearic acid (1906.71 ± 235.23 μM), were upregulated in psoriasis patients and decreased significantly after anti-IL-17A mAb treatment." (PMID 38185620, 2024). "In contrast to other studies that observed significant differences in IL-23 levels, our results indicate a possibly more decisive role of IL-17A in the dynamics between psoriasis and metabolic syndrome." (PMID 39202262, 2024). "Nevertheless, OSM stimulation significantly upregulated NF-κB inhibitor-ζ (IκBζ) expression, a crucial mediator of IL-17A signaling in psoriasis, thereby possibly providing an additive effect on IL-17A’s effect in HNECs and fibroblasts." (PMID 39361432, 2024). "Early studies, identified TNF-α is a key trigger of the innate inflammatory pathway in psoriasis, and as the understanding of the disease has advanced, the IL-23/IL-17A axis at the core of psoriasis pathogenesis." (PMID 38917217, 2024). "Current treatment strategies for managing psoriasis include the use of biologic agents that target IL-17A, such as secukinumab, ixekizumab, and brodalumab." (PMID 38892253, 2024). "Regarding the management of patients who experience a phenotypic transformation of psoriasis while on IL-17A inhibitors, literature suggests that the core principle is to discontinue the IL-17A inhibitor." (PMID 38695018, 2024). "Estradiol can inhibit the production of IL-1β by macrophages, and IL-1β is necessary for the generation of IL-17A in the psoriasis model." (PMID 39703508, 2024). "In the ECLIPSE study, a head-to-head clinical trial comparing IL-23p19 blockade with guselkumab and IL-17A blockade with secukinumab for the treatment of moderate-to-severe psoriasis in adults." (PMID 38405187, 2024). "This study confirmed that IL-17A primarily had a pro-inflammatory function in the concurrent presence of psoriasis and atherosclerosis." (PMID 39104857, 2024).
psoriasis (continued). "Serum concentration of HMGB1, TLR4, IL‐23, and IL‐17A were all positively correlated with psoriasis patients' PASI (r = 0.66, 0.68, 0.65, and 0.65, respectively, all p < .001)." (PMID 38414294, 2024). "Research has demonstrated that cytokines, such as IL-17A and IFN-γ, can enhance the secretion of EVs in HaCaT cells, indicating the potential role of EVs as integral components in the psoriasis-associated micro-environment." (PMID 39771564, 2024). "The crucial role of IL‐17A in the pathological conditions of psoriasis has been strongly supported, which is produced predominantly by Th17 cells." (PMID 38414294, 2024). "Recent developments include treatments that target both IL-17A and IL-17F in the psoriasis field, though each cytokine’s impact on internal organ damage is still under debate." (PMID 39519167, 2024). "Serum lipidomics analysis of psoriasis patients receiving pretherapy and posttreatment with anti-IL-17A mAb showed that the treatment ameliorated the skin lesions and regulated the dysregulated metabolism of LCFAs." (PMID 38185620, 2024). "IL-17A is considered a major ‘driver’ of pro-inflammatory cytokines in the pathogenesis of psoriasis, as it can activate keratinocytes and promote their hyper-proliferation." (PMID 39610686, 2024). "Adding evidence to mouse atopic dermatitis model, results of mouse IMQ-induced acute psoriasis model kept showing the better efficacy of dual-blocking IL-17A and IL-36R." (PMID 39600699, 2024). "The results showed that INM-A can significantly improve the skin condition of mice with psoriasis, reduce the levels of IL-17A, and inhibit polarized Th17 cells." (PMID 39338338, 2024). "Overall, this study provided valuable insights into the effects of serum LCFA metabolism in psoriasis patients treated with anti-IL-17A mAb and emphasized the importance of targeted metabolic profiling in comprehending disease mechanisms." (PMID 38185620, 2024). "IR significantly reduced the mRNA expression of IL-17A (MD = −2.27, p = .0066, 95% CI [−3.92; −0.63]) and IL-23 (MD = −5.36 [−13.74; 3.03], p = .01, 95% CI [−13.74; 3.03]) in psoriasis-like mice compared to those of the controls." (PMID 39316667, 2024). "In an in vitro model using IFN-γ/IL-17A/IL-22-stimulated HaCaT cells, leucosceptoside A effectively mitigated psoriasis-related inflammation by suppressing the PI3K/AKT signaling pathway." (PMID 38892253, 2024). "Lithium was switched to valproate, and treatment with secukinumab, an IL-17A inhibitor, was initiated, resulting in significant improvement in both psoriasis and mental health." (PMID 39184643, 2024). "Kaempferol also reduced the proportion of IL-17A + CD4+ T cells in the spleen and lymph nodes of mice with psoriasis caused by IMQ." (PMID 39296901, 2024). "During psoriasis pathogenesis, the epidermal microenvironment is enriched with inflammatory factors such as IL-17A and IL-17F, which can induce the expression of DAMPs in keratinocytes." (PMID 38255845, 2024). "The Multi-Analyte Flow Assay test showed that IMQ-induced psoriasis in mice had a notable effect on reducing IFN-γ, TNF-α, IL-9, IL-17F, IL-22, and IL-17A psoriasis-related inflammatory cytokines in the APLNs, Cal/Bms, and FA groups." (PMID 39534602, 2024). "The two most common are utilization of (i) a cytokine cocktail characteristic of psoriasis—IL-17A, IL-22, IL-1α, oncostatin M, and TNFα—so called M5, or (ii) imiquimod." (PMID 38672088, 2024). "Given the increasing use of IL-17A antagonists in psoriasis treatment, it is crucial to monitor for rare adverse reactions, including the paradoxical induction of pustular psoriasis." (PMID 38695018, 2024). "Third, γδ T cell-mediated production of IL-17A can also play a role in cutaneous pathology, driving tissue damage in psoriasis and dermatitis." (PMID 38543790, 2024). "Anti interleukin (IL)-17A therapy is a common and effective treatment for psoriasis, but there are also risks of infection." (PMID 38813385, 2024).
psoriasis (continued). "IL-36 signaling is crucial in IL-17A-induced psoriasis as it contributes to keratinocyte hyperproliferation and immune cell infiltration." (PMID 38892253, 2024). "IL-17A inhibitors induce a phenotypic transformation in psoriasis, predominantly to palmoplantar pustulosis." (PMID 38695018, 2024). "High levels of H3K9 and H3K27 acetylation have been found in the IL17A promoter region in the immune cells of patients with psoriasis; they would promote Th17 differentiation and psoriasis development." (PMID 38256115, 2024). "T17 cells, which secrete the proinflammatory effector molecules IL-17A and IL-17F, are a significant source of IL-17A in psoriatic skin and play a pivotal role in psoriasis pathogenesis." (PMID 39114670, 2024). "IL-17A produced by Th17/Tc17 cells is a key player in psoriasis pathogenesis; it acts on keratinocytes by inducing the secretion of chemokines and inflammatory molecules that can recruit neutrophils, macrophages, and more T cells to the site of inflammation." (PMID 37953417, 2024). "Psoriasis is an IL-17A and IL-23 cytokine-driven autoimmune skin disease mediated by the adaptive and innate immune systems." (PMID 38542915, 2024). "IL-17A is a key pro-inflammatory cytokine in the pathogenesis of psoriasis, and anti-IL-17A is an effective treatment for psoriasis." (PMID 39559368, 2024). "The pivotal roles of Th17 cells and IL-17A in psoriasis pathogenesis have been extensively recognized." (PMID 38617532, 2024). "This study aimed to measure the associations between inflammatory biomarkers, IL-17A, TNF-α, hs-CRP, and atherosclerosis in patients with psoriasis." (PMID 39104857, 2024). "It was reported that pro-inflammatory cytokines and mediators such as IL-17A, IL-22, IL-23, IL-6, IL-1β, and p65 play an important role in the development and maintenance of psoriasis." (PMID 39296901, 2024). "The established in situ derivatization method for analysing LCFAs with a GC–MS platform was utilized to conduct serum lipidomics analysis of healthy volunteers and psoriasis patients receiving pretherapy and posttreatment with of anti-IL-17A mAb." (PMID 38185620, 2024). "While IL-17A is more potent, IL-17F is more abundant in skin lesions of psoriasis (by approximately 30-fold), and can drive inflammation independently of IL-17A." (PMID 39459016, 2024). "Remarkably, treatment of 17A-Lytaca markedly decreased the mRNA expression of IL-17A and its downstream psoriasis-related inflammatory cytokines in the skin lesion, including IL-6, CCL-20, and IL-22, compared with the positive group." (PMID 38396109, 2024). "The serum levels of HMGB1, TLR4, IL‐23, and IL‐17A in psoriasis patients were significantly higher than healthy controls, especially in severe patients, and positively correlated with the severity index." (PMID 38414294, 2024). "According to the British Association of Dermatologists Guidelines for Biologic Therapy for Psoriasis 2020, three commonly used biological agents were selected: the IL-17A inhibitor SEC, IL-12/23 inhibitor UST and TNFα inhibitor ADA." (PMID 38472183, 2024). "No or statistically insignificant differences were observed between psoriasis patients and healthy controls for interleukin-12 (IL-12), interleukin-17a (IL-17a), interleukin-22 (IL-22), and interleukin-23 (IL-23)." (PMID 38668313, 2024). "This downregulation was suggested to contribute to the pro-inflammatory environment of psoriasis due to excess IL-17A signaling." (PMID 38402257, 2024). "This case appears to be the first documented instance of effective anti-IL-17A/IL-17F antibody treatment in a psoriasis patient undergoing HD, with a sustained positive response for eight months." (PMID 38673523, 2024). "Cellular uptake analysis revealed that IL-17A, a cytokine that plays a central role in the pathogenesis of psoriasis, enhanced unprotected Glu-4-ZnPc uptake by 56.3%, while GLUT1 inhibitor BAY-876 reduced its accumulation by 23.8%." (PMID 38931958, 2024).
psoriasis (continued). "Genetic ablation of AIM2 reduced the development of IMQ-induced psoriasis by decreasing the production of type 3 cytokines (such as IL-17A and IL-23) and infiltration of immune cells into the inflammatory site." (PMID 39352743, 2024). "HMGB1, TLR4, IL‐23, and IL‐17A serum concentrations in psoriasis patients were significantly elevated compared with those in healthy controls (t = 7.716, 2.433, 4.443, and 10.339, respectively, all p < .05 or .01)." (PMID 38414294, 2024). "This exacerbates skin inflammation, as CCL20, which originates from IL-17A-stimulated keratinocytes, attracts IL-17A-producing Th17 cells, perpetuating a vicious feed-forward cycle that culminates in a fully developed state of psoriasis." (PMID 38617532, 2024). "This study utilized the established in-situ derivatization method to conduct a targeted lipidomic analysis of LCFAs in serum samples from healthy volunteers and psoriasis patients receiving pretherapy and posttreatment with anti-IL-17A mAb." (PMID 38185620, 2024). "Later, LCs were identified as the main source of IL-23 that is required to activate IL-17A-producing γδ T cells in an imiquimod-induced mouse model of psoriasis." (PMID 38791342, 2024). "In an IMQ‐induced psoriasis model, Camk2g–/– mice exhibited significantly weakened psoriasis‐like manifestations and decreased γδT‐cell IL‐17A production relative to wild‐type (WT) mice." (PMID 38544478, 2024). "On the other hand, MUFAs, represented by palmitoleic acid (18.42 ± 2.84 μM), were downregulated in psoriasis patients but showed a significant increase after anti-IL-17A mAb treatment (22.14 ± 4.79 μM)." (PMID 38185620, 2024). "Clinical trials investigating the blockade of IL-17A have been conducted in RA patients, demonstrating modest efficacy compared to its effects in psoriasis, psoriatic arthritis, and spondylarthritis." (PMID 39507540, 2024). "Psoriasis is a chronic immune‐mediated inflammatory disease, in which IL‐17A is regarded as a preponderant inflammatory cytokine mediating its pathogenesis." (PMID 38414294, 2024). "There was a significant increase in IL-17F and IL-17A production in co-cultures of psoriasis skin-homing CLA+ T cells with epidermal cells when stimulated with IL-15 and IL-23This response was reduced around 50 to 80% by blocking HLA class I and II molecules." (PMID 38405187, 2024). "Overexpression of miR-378a (also upregulated in psoriasis) would be induced by IL-17A via the NF-kB pathway." (PMID 38256115, 2024). "Of particular importance, IL-17A emerged as a central cytokine in the pathogenesis of psoriasis, driving the proliferation of epidermal keratinocytes." (PMID 38605947, 2024). "The markers IFN-γ, IL-13, IFN-γ/IL13, IL-17A/IL-13, IFN-γ/IL4, and IL-17A/IL-4 are representative of predicting the efficacy of psoriasis treatment." (PMID 38791078, 2024). "A clinical trial supports our study finding where administration of ustekinumab, an anti-IL-23A monoclonal antibody, or brodalumab, or anti-IL-17A blockers resulted in a significant reduction of anxiety and depression symptoms in psoriasis patients." (PMID 38956309, 2024). "The upregulation of several cytokines and kinases has been implicated in the pathogenesis of psoriasis, including tumor necrosis factor-α (TNF-α), IL-17A, IL-17F, and IL-23." (PMID 39459016, 2024). "One such therapy, secukinumab, which functions as an IL-17A inhibitor, has shown promising results in reducing vascular inflammatory markers in patients with psoriasis." (PMID 38892457, 2024). "Secukinumab (Cosentyx), an interleukin-17A-targeting biological agent, is commonly prescribed for psoriasis, psoriatic arthritis, and spondyloarthritis (SpA)." (PMID 38523953, 2024). "As a representative inflammatory skin disease occupied by large surface involvement, the occurrence and development of psoriasis is reported to be related to the disorder of many inflammation markers, such as IL-17A, IL-23, and TNF-α." (PMID 38893287, 2024).
psoriasis (continued). "Interleukin (IL)‐17A is the central pathological factor in the pathogenesis and development of psoriasis." (PMID 39660880, 2024). "Taken together, these findings provide additional insights into the differential mechanisms and impact of IL-23 versus IL-17A blockade in psoriasis." (PMID 39224116, 2024). "We therefore analyzed psoriasis patients before starting established systemic therapy (targeting IL-17A, IL-23, TNF-α, IL-12/23, and DMF) and for a follow-up up to 16 weeks in a single-center prospective study." (PMID 38127137, 2024). "Ixekizumab, a monoclonal antibody targeting IL-17A, is currently the only agent that demonstrates improvement in inverse psoriasis lesions." (PMID 39768472, 2024). "In the pathological condition of psoriasis, systemic IL‐17A elevation can trigger microglia activation, provoke pro‐inflammation mediators to release, evoke neuroinflammation, subsequently inhibit hippocampal neurogenesis, and result in depression." (PMID 39660880, 2024). "Currently, psoriasis is incurable with interleukin-17A (IL-17A) and IL-23 has been identified as a key driver of its progression." (PMID 39316667, 2024). "IL-17 is a pivotal cytokine in the pathogenesis of psoriasis, and antibodies that target IL-17A have been effectively employed in treatment." (PMID 39519167, 2024). "In the pathological condition of psoriasis, systemic IL‐17A elevation can trigger microglia activation, provoke pro‐inflammation mediators release, evoke neural inflammation effects, then inhibit hippocampal neurogenesis and result in depression development." (PMID 39660880, 2024). "Consistent with the increased Th17 cell percentage, rHMGB1 treatment resulted in a dose‐dependent promotional effect on IL‐17A mRNA and protein expression levels in psoriasis patients' PBMCs (F = 83.94 and F = 36.13, both p < .001)." (PMID 38414294, 2024). "IL-17A neutralization approaches have been used in many autoimmune diseases such as psoriasis and RA45,46." (PMID 38168103, 2024). "Psoriasis is a chronic and recurrent autoimmune disorder mediated by IL-17A+IL-22+ TRM cells, which trigger inflammation." (PMID 39193473, 2024). "Serum levels of several proinflammatory cytokines, including TNF-α,IFN-γ,IL-6,IL-8,IL-12,IL-17A and IL-18 were elevated in individuals diagnosed with psoriasis compared to healthy controls, suggesting that psoriasis develops systemically." (PMID 38504983, 2024). "Baseline serum IL-17A, IL-17F, and IL-22 levels were shown to be higher in patients with moderate-to-severe psoriasis than in healthy controls." (PMID 39114670, 2024). "IL-17A plays a well-defined role in the pathology of psoriasis, psoriatic arthritis, and ankylosing spondylitis." (PMID 39076985, 2024). "Regarding the IL-17A blockade, clinical trials have shown mostly modest effects in RA, especially compared with the clinical efficacy observed in psoriatic arthritis, psoriasis and spondyloarthritis." (PMID 39744635, 2024). "TNF-α suppresses IFN-α secretion, induces DC maturation, and synergizes with IL-17A to regulate psoriasis-related cytokine and keratinocyte genes." (PMID 38892253, 2024). "In our study, we also noticed that in skin samples from mice with psoriasis, TCRγδlow cells were the main γδ T-cell subset that had high RORγT transcription levels and produced IL-17A." (PMID 38566145, 2024). "Our previous studies have confirmed the increased percentage of Th17 cells and expression levels of IL‐17A in the peripheral blood of psoriasis patients." (PMID 38414294, 2024). "Th17 and Tc17 cells activated by IL-23 produce a number of cytokines, including IL-17A, IL-17F, and IL-22, which act as effector cytokines that subsequently induce the expression of many psoriasis-related proteins." (PMID 39224116, 2024). "This study aimed to better understand the underlying mechanisms driving the differences between IL-23 and IL-17A blockade in patients with psoriasis and their implications for durability of clinical responses." (PMID 39224116, 2024).